RSPO3 (R-spondin 3)
Diseases named in the same sentence as RSPO3 in open-access papers (continued):
Sharing a sentence is not in itself a finding about the gene and the disease.
Insulin resistance (5 papers, 2016 to 2025). Increased resistance towards insulin, that is, diminished effectiveness of insulin in reducing blood glucose levels. "Second, hepatic Rspo3 induction ameliorates obesity-associated features, such as fatty liver change, diabetes, and insulin resistance including those impacting remote organs." (PMID 39854351, 2025). "In contrast, hepatic Rspo3 suppression exacerbates obesity-associated features, including glucose intolerance, insulin resistance, and fatty liver change." (PMID 39854351, 2025). "Herein, we demonstrated that modulation of hepatic Rspo3 improves obesity-associated features, including diabetes, insulin resistance, and fatty liver." (PMID 39854351, 2025). "Therefore, suppression of hepatic Rspo3 is associated with obesity-induced insulin resistance, systemically, as well as diabetes and changes in body compositions including the distributions of adipose tissue and skeletal muscle." (PMID 39854351, 2025). "Glucose tolerance and insulin tolerance tests indicated that hepatic Rspo3 induction improved obesity-induced glucose intolerance and insulin resistance, respectively, in ob/ob mice, observations also made in DIO and KK-Ay mice." (PMID 39854351, 2025). "In SO mice, Rspo3 induction ameliorated glucose intolerance and insulin resistance in obese mice, but these improvements were partially blocked by HV." (PMID 39854351, 2025). "In contrast, hepatic Rspo3 suppression through Cre-LoxP-mediated recombination system exacerbates diabetes due to glucose intolerance and insulin resistance, promotes fatty liver development and decreases skeletal muscle quality, resulting in obesity." (PMID 39854351, 2025). "Top loci in this cluster included several well-known associations with WHRadjBMI and insulin resistance including COBLL1, RSPO3, PPARG, and DNAH1012,47,54,55." (PMID 35773277, 2022). "In addition, recent studies have implicated HNF4A and PROX1-AS1 in insulin resistance and T2D, whereas loci harboring FAM13A, RSPO3, and EBPL have been associated with body fat distribution and hepatic steatosis." (PMID 39796632, 2025). "We find that viral-mediated induction of Rspo3 in hepatic tissue of obesity improves insulin resistance and prevents body weight gain by restoring attenuated organ insulin sensitivities, reducing adipose tissue enlargement and reversing overstimulated adaptive thermogenesis." (PMID 39854351, 2025). "Next, to examine whether HV influences Rspo3-induced improvement of glucose intolerance and insulin resistance in obese KK-Ay mice, we performed glucose tolerance and insulin tolerance tests." (PMID 39854351, 2025).
ovarian carcinoma (5 papers, 2021 to 2025). A malignant neoplasm originating from the surface ovarian epithelium. "RSPO3 has been implicated in ovarian cancer and has been suggested as candidate marker to predict ovarian cancer aggressiveness." (PMID 37238942, 2023). "Considering RSPOs in ovarian cancer, in silico analysis suggested relatively high RSPO1 mRNA expression in ovarian cancer, and another study reported high expression of RSPO1 and RSPO3 in ovarian tumor xenograft material." (PMID 34663878, 2021).
acute myeloid leukemia (4 papers, 2020 to 2024). Acute myeloid leukemia (AML) is a group of neoplasms arising from precursor cells committed to the myeloid cell-line differentiation. "RSPO3 has been reported to be associated with muscle fiber development, fat distribution, and the progression of acute myeloid leukemia." (PMID 37932819, 2023). "RSPO3-LGR4-maintained Wnt signaling is essential for the stemness of acute myeloid leukemia, and the clinical-grade anti-RSPO3 antibody eradicated leukemia stem cells, which might be effective in GI cancer." (PMID 33291655, 2020). "In addition to these results within solid tumor models, a recent study also showed beneficial effects of anti-RSPO3 treatment in certain acute myeloid leukemia PDX models, where anti-RSPO3 treatment effectively inhibited leukemia stem cells without harming healthy stem cells." (PMID 34663878, 2021).
leukemia (4 papers, 2020 to 2022). A malignant (clonal) hematologic disorder, involving hematopoietic stem cells and characterized by the presence of primitive or atypical myeloid or lymphoid cells in the bone marrow and the blood. "RSPO3/Lgr4 upregulates WNT/self-renewal target genes to block differentiation, which contributes to the aggressive leukemia phenotype, probably through the pCREB-CBP complex." (PMID 33946652, 2021).
breast tumors (3 papers, 2011 to 2022). "With regard to activation of the canonical Wnt pathway, we observed that RSPO3‐driven breast tumors expressed the Wnt/β‐catenin target genes Axin2, Wif1, Znrf3, and Ctnnb1 itself, however at significantly lower levels than their WNT1‐driven counterparts." (PMID 36106661, 2022). "In breast tumors, RSPO2 and RSPO3 were first identified as being involved in BCa initiation, proliferation, epithelial-mesenchymal transition, and metastasis." (PMID 34847079, 2022).
cholangiocarcinoma (3 papers, 2022 to 2026). A carcinoma that arises from the intrahepatic biliary tree (intrahepatic cholangiocarcinoma) or from the junction, or adjacent to the junction, of the right and left hepatic ducts (hilar cholangiocarcinoma). "However, the expression level of RSPO3 in cholangiocarcinoma (CCA) and its regulatory effect on tumor proliferation remain unknown." (PMID 37932819, 2023). "In this study, we investigated the characterization of RSPO3 in cholangiocarcinoma (CCA) by analyzing the GEO database." (PMID 37932819, 2023).
endometriosis (3 papers, 2025). The growth of functional endometrial tissue in anatomic sites outside the uterine body. "By integrating the results of SMR and colocalization analyses, we found that EPHB4 had a high level of correlation with the risk of developing endometriosis, while RSPO3 showed a moderate level of correlation." (PMID 40450304, 2025). "In addition, studies have found that estradiol can upregulate RSPO3, suggesting a potential association between RSPO3 and endometriosis, as endometriosis is an estrogen-dependent disease in which estrogen plays a crucial role throughout its progression." (PMID 40450304, 2025). "The causal role of RSPO3 in endometriosis positions it as a promising therapeutic target." (PMID 40893937, 2025). "We identified RSPO3 as a novel genetically supported risk factor for endometriosis." (PMID 40893937, 2025). "Repurposing oncology RSPO3 inhibitors thus offers a strategic approach to accelerate endometriosis drug development." (PMID 40893937, 2025). "Results from across our multi-omic analyses underscore the potential role of R-spondin 3 (RSPO3) in endometriosis pathophysiology as a previously-characterized promotor of fibrotic proliferation." (PMID 41377979, 2025). "In order to properly explore the activation of RSPO3 in endometriosis, we further performed HE staining and IHC staining." (PMID 40893937, 2025). "Finally, although experimental verification supports the role of RSPO3 in endometriosis, its specific molecular mechanism still requires further investigation." (PMID 40893937, 2025). "RSPO3 and FLT1 were found to be potentially associated with endometriosis within the proteome." (PMID 40893937, 2025). "Meanwhile, our study suggested that higher levels of EPHB4, RSPO3, FSHB, and SEZ6L2 were associated with an increased risk of endometriosis, while lower levels of CD109, SAA1, and SAA2 were also associated with an increased risk of endometriosis." (PMID 40450304, 2025). "After colocalization analysis, we identified that EPHB4 is considered to support high-level evidence of colocalization with endometriosis (PPH4 = 0.993), while RSPO3 is considered to support moderate-level evidence of colocalization with endometriosis (PPH4 = 0.783)." (PMID 40450304, 2025). "There were three stromal cellular contexts in which the expressions of RSPO3, WNT4, and ESR1 were significantly different depending on endometriosis status." (PMID 41377979, 2025). "However, clinical and basic research on the relationship between RSPO3 and endometriosis remains lacking, necessitating further studies to explore their association." (PMID 40450304, 2025). "During the proliferative phase, all three were upregulated in nondecidualized stromal cells from donors with endometriosis; in the early secretory phase, WNT4 switched to being downregulated, and in the mid secretory phase, both WNT4 and RSPO3 were diminished." (PMID 41377979, 2025).
lung squamous cell carcinoma (3 papers, 2016 to 2021). "In support of this notion, there is a report suggesting an opposite pattern of RSPO3 expression between adenocarcinoma and squamous cell carcinoma of the lung, even though the significance of this difference with respect to patient outcomes is unclear." (PMID 30987640, 2019).
Obesity (3 papers, 2024 to 2025). Accumulation of substantial excess body fat. "Therefore, targeting Rspo3 is very important for achieving therapeutic innovations and applications for patients suffering from diabetes, obesity, and obesity-associated diseases." (PMID 39854351, 2025). "Most notably, hepatic Rspo3 reverses enlargement of WAT in obesity via a newly identified neuronal inter-organ linkage from the liver to adipose tissue." (PMID 39854351, 2025). "Outside the liver, hepatic Rspo3 induction ameliorated reduced skeletal muscle quality in obesity by restoring insulin signaling and up-regulating muscle PPARα expression and muscle fatty acid utilization." (PMID 39854351, 2025). "The localization of Rspo3-positive hepatocytes in obesity was rather widespread, extending from the pericentral zone to the periportal zone." (PMID 39854351, 2025). "Considering the data obtained from models of hepatic Rspo3 induction in obese mice, these results show obesity to influence the spatially regulated expression patterns of marker genes in the pericentral and periportal zones of the liver." (PMID 39854351, 2025). "Next, to investigate whether hepatic Rspo3 induction has any effects on obesity-related metabolic dysregulation, we administered Rspo3 adenovirus to obese (ob/ob) mice (obese Rspo3-mice)." (PMID 39854351, 2025). "Hepatic Rspo3 induction increased β2-adrenergic receptor (β2AR) and resultant PGC1α expressions in skeletal muscle, thereby suggesting the restoration of adrenergic signaling, and skeletal muscle quality, which had been impaired in the setting of obesity." (PMID 39854351, 2025). "Next, we examined whether hepatic Rspo3 expression has any effects on obesity-induced derangements of body composition including adipose tissue and skeletal muscle." (PMID 39854351, 2025). "Rspo3 expression analysis shows that Rspo3 expression patterns are spatiotemporally controlled in the murine liver such that it locates in the pericentral zones and converges after feeding, and the dynamics of these processes are disturbed in obesity." (PMID 39854351, 2025). "Interestingly, hepatic Rspo3 induction suppressed obesity-induced body weight gain for 7 and 23 days with decreased cumulative food intakes for 7 and 14 days after adenoviral treatment." (PMID 39854351, 2025). "RSPO3's involvement in modulating adipose tissue dynamics via the WNT signaling pathway may contribute to gene-environment interplay, potentially affecting body fat distribution patterns and susceptibility to metabolic diseases like obesity." (PMID 40166017, 2025). "Therefore, Rspo3, locally in the liver, functions as a key molecule suppressing the progression of obesity-related fatty liver, and possesses an inherent ability to influence the systemic management of body composition, leading to maintenance of glucose metabolism at the whole-body level." (PMID 39854351, 2025). "Based on these results, we can reasonably speculate that hepatic Rspo3 induction locally diminishes obesity-related fatty liver progression by balancing the degrees of lipogenesis, lipid oxidation, and glucose utilization (gluconeogenesis, glycolysis, and glycogenesis) in the liver." (PMID 39854351, 2025). "In addition, hepatic Rspo3 induction diminished enlargement of WAT in obese mice, while it restored sustained stimulation of BAT-mediated adaptive thermogenesis against obesity development." (PMID 39854351, 2025). "In lean models, but not in obesity, serum Rspo3 levels were up-regulated by feeding." (PMID 39854351, 2025). "Locally in the liver, hepatic Rspo3 induction, reconstituting metabolic zonation, revealed a novel inter-nutrient mechanism by which the balance between lipid and glucose metabolism is maintained, thereby playing an important role in suppressing obesity-related fatty liver progression." (PMID 39854351, 2025).
Obesity (continued). "However, a limitation of this study is that we did not strictly examine whether hepatic Rspo3 induction in obesity has effects more prolonged than those observed up to 23 days after adenovirus administration." (PMID 39854351, 2025). "We found that endogenous Rspo3 expressions in the liver and WAT, the major organs producing Rspo3, were decreased, while those in BAT and skeletal muscle were not, according to the degree of obesity." (PMID 39854351, 2025).
osteoporosis (3 papers, 2017 to 2025). A condition of reduced bone mass, with decreased cortical thickness and a decrease in the number and size of the trabeculae of cancellous bone (but normal chemical composition), resulting in increased fracture incidence. "Multiple proteins that showed strong evidence to be associated with osteoporosis-related traits were supported by previous studies, such as RSPO3, IDUA, SMOC2." (PMID 37448626, 2023). "Multiple RSPO3 genetic variants have been identified through GWAS, with SNPs such as rs13204965 showing a significant relationship with BMD, potentially increasing the risk of osteoporosis." (PMID 41264632, 2025). "Recent findings further suggest that RSPO3 could serve as a critical intermediary in the development of IBD-related osteoporosis by modulating immune cell functions and the expression of inflammatory factors." (PMID 41264632, 2025). "The results of the analysis on BMD and osteoporosis were subsequently structured, uncovering four shared genes in IBD: ZBTB40, RP1-135L22.1, RSPO3, and RP11-103J8.1." (PMID 41264632, 2025). "Clinical studies have highlighted a significant correlation between RSPO3 expression and BMD in IBD patients, offering new insights into the pathogenesis of IBD-related osteoporosis." (PMID 41264632, 2025).
adenoma (2 papers, 2017 to 2022). A neoplasm arising from the epithelium. "Surprisingly, infected Rspo3-KI mice showed dramatic changes in gland architecture, such as extreme gland elongation, formation of large cyst-like structures, and in 30% of mice, development of focal lesions in the base of corpus glands that were classified as adenoma by a veterinarian expert." (PMID 36099044, 2022).
diabetes (2 papers, 2024 to 2025). "Third, selective knockdown of hepatic Rspo3 exacerbates diabetes and fatty liver change, and then decreases insulin sensitivity in remote organs such as skeletal muscle and adipose tissue as well as in the liver." (PMID 39854351, 2025). "It is also reported that the Wnt/β-catenin signaling pathway is downregulated in diabetes due to decreased levels of R-spondin 3 (Rspo-3)." (PMID 38671406, 2024). "Therefore, modulating and restoring metabolic zonation by targeting the hepatic Rspo3 signaling pathway may lead to novel therapeutic strategies for diabetes and metabolic syndrome." (PMID 39854351, 2025).
fibrosis (2 papers, 2020 to 2023). the formation of excess fibrous connective tissue in an organ or tissue in a reparative or reactive process. "Finally, RSPO3 was found to be highly elevated in the active lesions of fibrotic tissues in mouse models of fibrosis and in patients with idiopathic pulmonary fibrosis (IPF) and nonalcoholic steatohepatitis (NASH)." (PMID 32160239, 2020). "Specifically, an anti-RSPO3 antibody, OMP-131R10, when dosed therapeutically, attenuated fibrosis in carbon tetrachloride (CCl4)-induced liver fibrosis, bleomycin-induced pulmonary and skin fibrosis models." (PMID 32160239, 2020). "After having established a functional role for RSPO3 in liver fibrosis, we next sought to examine if OMP-131R10 could be a therapeutic agent to treat fibrosis and whether OMP-131R10 possesses broad anti-fibrotic activity." (PMID 32160239, 2020). "Because of the severe phenotypes from RSPO gene knockout studies including embryonic lethality from RSPO3 gene disruption, we generated and used selective monoclonal antibodies against each of three RSPO proteins (RSPO1-3) to test their effects in animal models of fibrosis." (PMID 32160239, 2020).
intestinal cancer (2 papers, 2017 to 2023). "The combination of RSPO3 inhibition and taxane treatment provides an approach to effectively target oncogenic WNT signaling in a significant number of patients with colorectal and other intestinal cancers." (PMID 29127379, 2017).
intestinal tumor (2 papers, 2021 to 2023). "As a result of these fusion mutations, high levels of RSPO2 and RSPO3 are detected in tumours harbouring these mutations, and indeed, mice harbouring Rspo2 or Rspo3 fusion mutations develop intestinal tumours." (PMID 37048063, 2023). "Formal evidence for the causal oncogenic capacity of Rspo3 was provided by a mouse study where conditional Rspo3 overexpression consistently induced abundant intestinal tumor formation, demonstrating that augmentation of Rspo3 levels is causative in driving tumorigenesis." (PMID 34663878, 2021).
liver fibrosis (2 papers, 2020 to 2025). "Our understanding of the role of RSPO3 began when we tested three members of the RSPO family using specific monoclonal antibodies in well-established in vivo murine model of liver fibrosis." (PMID 32160239, 2020). "We demonstrated that only anti-RSPO3 antibody significantly ameliorated liver fibrosis through inhibition of the Wnt/β-catenin signaling, although all three RSPO proteins function primarily through the enhancement of the pathway." (PMID 32160239, 2020). "Our findings that RSPO3 is highly elevated in human fibrotic lungs and livers, and that RSPO3 levels are significantly correlated with disease severity, provide supporting evidence that RSPO3 may play a role in lung and liver fibrosis in human." (PMID 32160239, 2020). "RSPO3 expression was substantially decreased in HSCs isolated from models of toxic, biliary or MASLD-related liver fibrosis, progressively declining in advanced disease stages, alongside a reduction of RSPO3 protein." (PMID 40074890, 2025). "By contrast, MASLD and ALD, against which RSPO3, LGR4/5 and their downstream target β-catenin protect, represent the commonest forms of CLD and liver fibrosis in patients." (PMID 40074890, 2025).
metastatic disease (2 papers, 2019 to 2021). "In contrast, another group that studied gene expression data sets reported reduced levels of RSPO3 in prostate tumors compared to healthy tissue, with further expression loss in metastatic disease and RSPO3 loss correlating with an increased risk of relapse." (PMID 34663878, 2021).
multiple myeloma (2 papers, 2020). "For instance, the interaction of SDC4 and RSPO3 was shown to regulate WNT/planar cell polarity (PCP) signaling during Xenopus gastrulation by a process that requires clathrin-mediated endocytosis, and SDC1 was shown to promote signaling in multiple myeloma by presenting WNTs and RSPOs." (PMID 32432544, 2020). "In Xenopus, RSPO3 has been shown to interact with Syndecan4 to induce non-canonical (PCP) signalling and Syndecan1 has been suggested to present WNT and R-spondins in multiple myeloma." (PMID 32324134, 2020).